IL6 (interleukin 6)
Diseases named in the same sentence as IL6 in open-access papers (continued):
Sharing a sentence is not in itself a finding about the gene and the disease.
COVID-19 (continued). "In this study, we aimed to evaluate in patients with COVID-19 in Romania the association between lung injury on CT scans and changes in inflammatory markers such as CRP (C-reactive protein), IL-6 (interleukin 6), procalcitonin, and NLR (neutrophil to lymphocyte ratio)." (PMID 35893392, 2022). "Interleukin 6 (IL-6) belongs to a broad class of small proteins involved in the regulation of various homeostatic and pathological processes, including embryonic development, wound healing and ageing, inflammation, and immunity, including COVID-19." (PMID 36429126, 2022). "Th1 cytokines and IL-6 appear to be involved in the inflammatory response during COVID-19." (PMID 36016309, 2022). "IL-6 is evidently leading the development and effects of “cytokine storm” in severe COVID-19, while it has a major tumor-promoting role as it activates the IL-6/JAK/STAT pathway and induces the invasive and angiogenic properties of cancer via interactions with other cytokines." (PMID 36077865, 2022). "D-dimer and IL-6 are significant predictors of mortality in ILD patients infected with COVID-19." (PMID 36106257, 2022). "As in COVID-19, IL-6 and CRP show the best predictive utility." (PMID 35622838, 2022). "SARS-CoV-2 infection induced CCL2, CCL5 and IL-6 release from placental cells, which might promote the cytokine storm in pregnant women with COVID-19." (PMID 36414950, 2022). "Anti-cytokine autoantibodies (e.g., antibodies against IFNα, IFNε, IL-6, IL-22, GM-CSF and TNFα) may also provide a potential target for COVID-19 treatment." (PMID 36341384, 2022). "In addition, high levels of IL-1β and IL-6 were observed in patients with severe COVID-19 than other patients." (PMID 35168674, 2022). "Moreover, COVID-19 patients who were admitted had a substantial accumulation of inflammatory cytokines, including TNF-а, IL-6, IL-2, and IL-10, especially in severe COVID-19." (PMID 35573725, 2022). "Moreover, COVID-19 patients have an enhanced level of chemokines and cytokines, such as interleukin-1 receptor antagonist (IL-1RA), IL-2, IL-6, IL-7, IL-8, IL-9, IL-10, IFN-γ, TNF-α, and the granulocyte-macrophage colony-stimulating factor." (PMID 36092161, 2022). "Transcriptome studies have reported decreased levels of SOCS-3 in myeloid cells during COVID-19, which could lead to an immunosuppressive response to IL-6-mediated STAT3 activation during COVID-19." (PMID 35421120, 2022). "Moreover, we observed that proinflammatory cytokines involved in lymphocyte and macrophage activation (IL-1β, IL-6, IL-16), Th2 (IL-4), and Th17 (IL-17A) responses were also increased in urine samples of COVID-19 patients." (PMID 36359444, 2022). "Therefore, the current study aimed to investigate lncRNAs, particularly NEAT1 and TUG1, and their association with IL-6, CCL2, and TNF-α in COVID-19 patients with moderate and severe disease." (PMID 35982898, 2022). "Elevated IL-6 levels are correlated with a poor prognosis of COVID-19 patients." (PMID 35782361, 2022). "Each of IL-6, lymphocytes, and neutrophils might represent major factors in the severity of COVID-19 and IL-6 plays the main role in inducing the inflammatory and pathophysiology process that is known as the cytokine storm." (PMID 35721343, 2022). "Furthermore, increases in TNF-α and IL-6 immunological activation are significant and independent predictors of severity and mortality in COVID-19." (PMID 35664675, 2022). "Moreover, the IL-26 concentration displayed a modest positive correlation (r = 0.36) with that of IL-6 when all the subjects in the COVID-19 and Control groups were pooled together." (PMID 36466824, 2022). "Furthermore, AMP5A suppresses a distinct set of pro-inflammatory cytokines (including IL-1β, IL-6, IL-12, and CXCL10) associated with COVID-19 and pro-inflammatory NF-κB activation." (PMID 35261923, 2022).
COVID-19 (continued). "Several studies suggest that an elevated level of IL-6 correlates with a severe response to COVID-19 53, 54; that is, IL-6 may be a predictor for COVID-19 patients who develop pulmonary fibrosis." (PMID 36147459, 2022). "It is known that COVID-19 could induce an aberrant surge in plasma IL-6 levels, culminating in the “cytokine storm” and systemic hyperinflammation." (PMID 35966846, 2022). "In this regard, there is a hypothesis that elevated levels of IL-6 following the viruses' entry into the immune system may be one of the reasons for elevated TH17 cells in COVID-19 patients." (PMID 35765103, 2022). "The increased levels of IL-6 can further upregulate the cytokine storm in COVID-19 patients." (PMID 36353605, 2022). "Moreover, acute inflammatory cytokine (IL-6) release in COVID-19 patients is known to precipitate acute kidney injury (AKI), glomerular pathology, acute tubular necrosis, leading to PCT damage, and electrolyte abnormalities." (PMID 35960124, 2022). "We propose, therefore, that direct targeting of LRG1 may be an alternative, or complementary, therapy for COVID-19-related pulmonary microvascular complications and other disease where the vasculature is disrupted by IL-6." (PMID 35318338, 2022). "Moreover, these laboratory variables are of great interest in COVID-19 patients because COVID-19 infection causes cytokine storm leading to elevated inflammatory markers, such as ferritin, LDH, CRP, and IL-6." (PMID 35562677, 2022). "The IL-8 concentration can make a distinct difference between severe progression and recovery in SARS-CoV-2 infection, and IL-8 could be a more appropriate marker to determine the status of COVID-19 compared with IL-6." (PMID 35782361, 2022). "In the acute COVID-19 group, patients with the severe form had higher IL-6 levels (p=0.0260)." (PMID 35846757, 2022). "Additionally, it has been reported that the SARS-CoV S protein can upregulate IL-6 and TNF-α expressions through the NF-κB signaling pathway, increasing the levels of inflammatory factors in COVID-19 patients, and causing serious lung damage." (PMID 36364151, 2022). "Based on these evidences, understanding the consequences of the concomitant presence of risks factors (IL-6 + AZM + HCQ) on the arrhythmic risk, is urgently needed to inform the clinical decisions for not only COVID-19 patients but also for patients with other autoimmune/inflammatory conditions." (PMID 35058480, 2022). "Correlation of antiviral antibodies and the proinflammatory mediator IL-6 in COVID-19 patients." (PMID 35582921, 2022). "The IL-6/IL-10 ratio describes the inflammatory potential in COVID-19." (PMID 39931658, 2022). "Accordingly, applying neutralizing antibodies to target IL-6- mediated inflammatory responses may be a life-saving strategy for COVID-19 patients." (PMID 35619180, 2022). "Levels of IL-6, CXCL10, CXCL11, IFNγ and MCP-3 were > fourfold higher in the serum of patients with COVID-19 versus healthy controls and linked with observations of inflammatory and viral-induced interferon response genes detected in nasopharyngeal swab samples from the same patients." (PMID 35303909, 2022). "In addition, the concentrations of IL-6 in patients with severe COVID-19 was usually tens of pg/mL, which was similar to our results and far lower than those in patients with septic shock or CRS induced by Chimeric Antigen Receptor (CAR) T-cell infusion." (PMID 35185571, 2022). "A large study at the Mount Sinai Institute of New York followed up with 1484 patients hospitalized for suspected or confirmed COVID-19 up to 41 days after admission: IL-6 and TNF-alpha at the time of hospitalization confirmed their predictive value on disease severity and death risk." (PMID 36422198, 2022).
COVID-19 (continued). "Focusing on the potential impact of pharmacological treatment for COVID-19 on the occurrence of thrombosis in the present cohort, patients who were administered corticosteroid therapy and anti-IL6 or anti-IL6R monoclonal antibody were significantly more often diagnosed with thromboembolism." (PMID 36028857, 2022). "Furthermore, HD induces inflammation; specifically, IL-6 levels are increased after dialysis Moreover, patients with diabetic nephropathy are particularly susceptible to inflammatory reactions induced by IL-6, which suggests that IL-6 may be a key mediator in HD patients with COVID-19." (PMID 34436742, 2022). "Moreover, it has been well described that elevation of some serum inflammation biomarkers, such as interleukin-6 (IL-6) and necrosis factor alpha (TNF-α), among others, is associated with mortality in COVID-19 patients." (PMID 35746958, 2022). "The observed high levels of IL-6 and its circulating receptor have been responsible for the deleterious effects on the liver sinusoidal endothelial cells, and blood clotting, and for contributing to liver injury in COVID-19 patients." (PMID 36439786, 2022). "Higher IL-6 levels (as reported in plasma of moderate and severe COVID-19 patients) could be responsible for the activation of IDO." (PMID 36250098, 2022). "Though the specific cause of hyperferritinemia is unknown, higher proinflammatory cytokines such as TNF-alpha, IL-1, IL-6, etc., in COVID-19 patients are thought to enhance serum ferritin production." (PMID 35982484, 2022). "Infection with SARS-CoV-2 leads to COVID-19, the severity of which is partly due to host immune responses, including the release of proinflammatory cytokines, such as interleukin (IL)-6, IL-18 and tumor necrosis factor (TNF), with serious biological and clinical consequences." (PMID 35336907, 2022). "Moreover, although CXCL10 and IL-6 were universally found with increased levels in all COVID-19 subgroups, the magnitude order was higher in MV and Death compared to nMV and Discharge." (PMID 36451835, 2022). "In the immune response to SARS-CoV-2 infection, excessive NOTCH signaling may promote IL-6 and inflammatory pathways that can exacerbate morbidity and severity of COVID-19." (PMID 35992174, 2022). "On the other hand, some evidence quarrel about the usage of anti-IL-6 agents for COVID-19 patients." (PMID 35619180, 2022). "In addition to IL-6, there are reports showing that compared to controls, IL-1b levels are also elevated in patients with COVID-19." (PMID 36404512, 2022). "Moreover, KL-6 has been positively correlated with CRP and IL-6 levels in patients with a severe course of COVID-19." (PMID 36362828, 2022). "High levels of IL-6, CRP, and hypertension could be considered as important risk factors for evaluating COVID-19 severity." (PMID 36010198, 2022). "The GSEA analysis suggests that Virofree could reverse COVID-19 signatures by reducing CRS through inhibition of IL-6 and activation of an interferon-β signaling pathway to reduce ARDS-associated COVID-19." (PMID 35860023, 2022). "In line with our findings, higher levels of IL6 have been reported also by other studies in the periphery and in the cerebrospinal fluid (CSF) of COVID-19 patients, as well as in children with acute encephalitis-like syndrome during infection with coronavirus-OC43." (PMID 36195636, 2022). "Therefore, the blockade of IL-6 or its receptor using drugs such as tocilizumab can be a potential therapeutic strategy for COVID-19." (PMID 35252273, 2022). "Therefore, inhibitors of IL-6 and its receptor have been proposed as interventions for patients with COVID-19." (PMID 35277472, 2022). "Moreover, the authors observed that increased levels of blood interleukin 6 (IL-6), cardiac troponin I and lactate as well as lymphopenia were more commonly seen in patients with a severe COVID-19 illness." (PMID 35409617, 2022).
COVID-19 (continued). "Similarly, COVID-19 plasma exosomes from patients in both their early and late hospitalization stimulated the expression of IL-6, IL-8, and TNF-α in CD14+ monocytes." (PMID 36526691, 2022). "Thus, we plotted the levels of NP, CRP, and IL-6 against the days after onset in the COVID-19 patients." (PMID 35529699, 2022). "Though promising outcomes have been reported following treatment of patients with COVID-19 with immunomodulators (e.g., IL-6 inhibitors), further clinical trials are required to understand the efficacy and safety of these drugs according to disease stage and severity." (PMID 35047633, 2022). "From these data, it can be postulated that in COVID-19 patients increased levels of aldosterone activate the NF-κB signaling pathway via the MR, which activates the expression of pro-inflammatory cytokines such as TNFα and IL-6." (PMID 35867189, 2022). "High levels of cytokines, such as IL-6, IL-1β, TNF-α, and IFN-γ, have been detected in COVID-19 patients, causing a syndrome called cytokine storm, which is believed to be the main cause of tissue damage in the pathophysiology of COVID-19." (PMID 35062298, 2022). "IL-6, through the induction of pro-inflammatory chemokines and cytokines, plays a key role in the development and maintenance of inflammation, acting as a pioneer of the hyperinflammatory condition and cytokine storm in severe COVID-19." (PMID 35645219, 2022). "For the majority of these cytokines and chemokines, including those that are typically associated with macrophage activation syndrome (IL-6, IL-18, IFN-γ, TNF-α, CXCL9), the increase was less pronounced in COVID-19 critical condition than in macrophage activation syndrome patients." (PMID 35645351, 2022). "The complete blood cell count results in severe COVID-19 were entirely consistent with human patients, while the neutrophilia and lymphopenia accompanied by high-level pro-inflammatory cytokine IL6 were observed in the BMA8- or C57MA14-infected aged BALB/c mice." (PMID 35197985, 2022). "When comparing IL-6 levels in patients with varying degrees of severity of COVID-19, it was shown that in patients with severe and extremely severe forms of the disease, the level of IL-6 in the blood serum is almost three times higher than in patients with a moderate course of the disease." (PMID 35736649, 2022). "Others risk factors involved with HAI development among COVID-19 patients admitted to ICU in our study were those prescribed anticoagulants, antithrombotic, antivirals and IL-6 inhibitors including tocilizumab, with tocilizumab typically prescribed to severe or critical patients." (PMID 36551463, 2022). "IL-6 levels have a substantial predictive value for mortality in COVID-19 ICUs." (PMID 35784318, 2022). "In severe COVID-19 patients, inflammatory mediators correlate with markers of oxidative stress, the strongest correlation was observed between oxidative stress index and IL-6." (PMID 35571085, 2022). "Targeting crucially involved molecules such as IL-6, and inhibiting signaling pathways involved in cytokine production appear to be promising approaches; indeed, corticosteroids and IL-6 blockade (with tocilizumab or sarilumab) are now standard of care in patients with severe COVID-19." (PMID 35327420, 2022). "Pre- and post-treatment with UC-MSCs, the COVID-19 patient's blood cell amount, IL-6, oxygenation index (OI), and partial pressure of oxygen observed a continuous reduction in total neutrophils and IL-6; lymphocyte amount, the OI, and partial pressure of oxygen slowly increased." (PMID 35715852, 2022). "Elevated IL-6 is also known to be associated with CRS and induces a more severe disease and worse outcome for patients with COVID-19." (PMID 35242747, 2022). "Therefore, the use of the IL-6 type of biomarker, which is now used for monitoring disease prognosis in COVID-19 patients, should be revisited as a prognostic marker in malaria-endemic regions." (PMID 36415655, 2022).
COVID-19 (continued). "The beneficial effects of IL-6 inhibitors, particularly anti-IL-6 mAb, in the management of COVID-19 have long been debated owing to discrepancies in study results due to heterogeneity in sample size, patient series composition, treatment protocols, concomitant therapies, and disease severity." (PMID 35645219, 2022). "Current detection for COVID-19 is primarily relies on techniques including, RT-PCR, chest X-ray, computed tomography (CT) scans, blood-based biomarkers (elevated C-reactive protein, low lymphocyte counts, high interleukins (IL-6/IL-10))." (PMID 36045375, 2022). "Likewise, overproduction of IL-6 reported to drive the immune dysregulation in severe COVID-19 patients." (PMID 36422492, 2022). "Indeed, the dynamic change of IL-6 level can be used as a potential biomarker for a severe case of COVID-19." (PMID 35197994, 2022). "The most common cytokine elevated in critically ill COVID-19 patients was Interleukin-6 (IL-6)." (PMID 35662927, 2022). "Moreover, the population of classical inflammatory monocytes – CD14+CD16+ subsets that produce IL-6 – was significantly elevated in COVID-19 patients hospitalized in the intensive care unit compared to those patients who were not." (PMID 36069182, 2022). "Furthermore, heparin binds to COVID-19 spike proteins and IL-6, which are elevated in COVID-19 patients." (PMID 35722697, 2022). "Tocilizumab, an IL-6 antagonist, revealed good capacity in inhibiting inflammation and cytokine storms in COVID-19 and various clinical studies have verified the beneficial effect of IL-6 and its receptor antagonists in treating severe and critical COVID-19 patients." (PMID 35237162, 2022). "In our study, Remdesivir and Lopinavir as antiviral treatments, and Tocilizumab as an Il-6 inhibitor, were administered to the COVID-19 group in accordance with international protocols from the time of data collection and on the recommendation of the infectious disease physician." (PMID 35208760, 2022). "Since both stroke and COVID-19 lead to increases in circulating IL-6 and CRP, their combination could significantly exacerbate inflammatory mediator concentration and worsen overall patient outcome." (PMID 38566903, 2022). "Furthermore, given the various immune-modulatory pathways of MSCs, a gradual decrease in IL-6 levels has been proposed to be a biologically valid surrogate of treatment success in COVID-19 patients." (PMID 35365239, 2022). "Several biomarkers, such as procalcitonin, C-reactive protein, interleukin-6 (IL-6), and monocyte chemotactic protein-1 (MCP-1) have been found to be associated with prognosis or disease severity in patients with COVID-19." (PMID 35242747, 2022). "We observed a trend toward an increase in the percentage of IL-6+ monocytes and a decrease in the percentage of CD4+IFN-γ+ and CD8+IFN-γ+ lymphocytes in COVID-19 patients, indicating that mononuclear cells support a high concentration of IL-6 and a low response to IFN-γ." (PMID 35901034, 2022). "Similarly, alveolar capillary endothelial cells showed strong and diffuse immunoreactivity for IL-6 and IL-15 in the COVID-19 group (p < 0.001)." (PMID 34463916, 2022). "IL6-inhibitors in severe COVID-19 patients were being tested." (PMID 36672763, 2022). "Moreover, a prognosis was poor for patients with severe COVID-19 if they had a consistently high level or trend for an increase in neutrophil frequency and increased serum concentrations of IL-6, procalcitonin, D-dimer, SAA, and CRP during hospitalization." (PMID 35632823, 2022). "The excessive production of cytokines and chemokines such as interleukin-6, 12, 1β and interferon-γ by the organism in patients with severe COVID-19 may contribute to cardiac injury." (PMID 36148048, 2022). "IL-6 is one of the chief markers used in the management of COVID-19." (PMID 36366295, 2022).